ERVH48-1 (endogenous retrovirus group 48 member 1, envelope)
Description:
May play a role in trophoblasts syncytialization, the spontaneous fusion of their plasma membranes, an essential process in placental development. May negatively regulate cell-cell fusion by interacting with SLC1A5, the probable receptor on the cell surface of the fusogenic syncytin-1/ERVW-1.
Synonyms: C21orf105; HERV-Fb1; NDUFV3-AS1; SUPYN
Tractability: Small molecule: a structure with a bound ligand is known. Antibody: UniProt places it where antibodies can reach, with high confidence; its Gene Ontology location is reachable by antibodies, with high confidence; UniProt predicts a signal peptide or a membrane-spanning region.
Gene: Protein-coding gene on chromosome 21 (42,916,803 to 42,925,630, reverse strand). Ensembl gene ENSG00000233056.
Subcellular location: Secreted
Gene Ontology:
Molecular function: protein binding
Biological process: negative regulation of syncytium formation by plasma membrane fusion
Cellular component: extracellular region; plasma membrane
Homologues: Orthologues: chimpanzee ERVH48-1 (98% identical), macaque ERVH48-1 (88% identical).
Diseases named in the same sentence as ERVH48-1 in open-access papers:
ERVH48-1 is named in the same sentence as 19 diseases in open-access papers, as found by Europe PMC text mining. Sharing a sentence is not in itself a finding about the gene and the disease. The quoted sentences say what the papers report.
Down syndrome (2 papers, 2022 to 2023). "ERVH48-1 colocalizes with the Down syndrome critical region on chromosome 21, of which there are three copies in affected Down syndrome patients." (PMID 35732788, 2022). "Increased levels of ERVH48-1 transcripts and SUPYN proteins were detected in Down syndrome placentas when compared to gestational age-matched disomic control placentas (16–20 weeks)." (PMID 35732788, 2022).
lung carcinoma (2 papers, 2022 to 2024). "The result of quantitative real-time PCR showed that ERVH48-1 was upregulated in lung cancer cells." (PMID 36386793, 2022). "Results of qRT-PCR showed that ERVH48-1 was upregulated in lung cancer cells." (PMID 36386793, 2022). "Additionally, ERVH48-1 has been shown to influence disease outcomes, such as inhibiting breast cancer, prediction of recurrence-free survival in hepatocellular carcinoma, up-regulation of expression in lung cancer cells, and potentially playing a role in antiviral immunity." (PMID 39269631, 2024).
ischemic stroke (1 paper, 2020). A stroke disorder caused by obstruction of blood flow to the brain, due to thrombotic (local blood clot formation) or embolic (due to a blood clot or other material traveling from another site) event. "LINC01002 and ERVH48-1, as ceRNAs, affect the expression of target genes of ischemic stroke by competitively binding to the hsa-let-7f-5p family." (PMID 33490236, 2020). "We found that four key lncRNAs (LCMT1-AS2, ERVH48-1, LINC01002, and LINC00638) may be highly associated with the pathogenesis of ischemic stroke." (PMID 33490236, 2020).
prostate carcinoma (1 paper, 2024). A carcinoma that arises from epithelial cells of the prostate gland. "This suggests that ERVH48-1 may be a potential therapeutic target for treatment-resistant prostate cancer." (PMID 39269631, 2024).
ERVH48-1 also shares sentences with these, for which no sentence is quoted: preeclampsia (3 papers); fetal growth restriction (2); pregnancy-induced hypertension (2); breast carcinoma (1); cervical cancer (1); endometrial adenocarcinoma (1); hepatocellular carcinoma (1); Hypertension (1); infection (1); lung adenocarcinoma (1); multiple myeloma (1); perinatal disease (1); placental diseases (1); trisomy 21 (1); tumor (1).